TTC9B (tetratricopeptide repeat domain 9B)
Synonyms: FLJ30373
Tractability: PROTAC: its protein half-life has been measured.
Gene: Protein-coding gene on chromosome 19 (40,216,058 to 40,218,388, reverse strand). Ensembl gene ENSG00000174521.
Subcellular location (Human Protein Atlas): Mitochondria; Nucleoplasm; Vesicles
Genetic constraint (gnomAD): Loss-of-function variants: 12 observed, 18.08 expected, observed/expected ratio (o/e) 0.66, 90% interval 0.42 to 1.08. The upper end of that interval is the gene's LOEUF score, 1.08, which puts it in group 4 of 6, group 1 being the genes least tolerant of losing a copy. Missense variants: 316 observed, 290.31 expected, observed/expected ratio (o/e) 1.09, 90% interval 0.99 to 1.2. Synonymous variants: 156 observed, 128.5 expected, observed/expected ratio (o/e) 1.21, 90% interval 1.07 to 1.39.
Homologues: Orthologues: chimpanzee TTC9B (100% identical), macaque TTC9B (98% identical), guinea pig TTC9B (93% identical), dog TTC9B (92% identical), mouse Ttc9b (91% identical), pig TTC9B (91% identical), rat Ttc9b (91% identical), rabbit TTC9B (62% identical), zebrafish ttc9b (51% identical), tropical clawed frog ttc9b (49% identical), Caenorhabditis elegans fkb-4 (8% identical), Caenorhabditis elegans fkb-5 (8% identical). Paralogues in human: TTC9 (49% identical), TTC9C (33% identical), FKBP4 (15% identical), FKBP5 (15% identical), FKBP8 (15% identical), FKBPL (15% identical), FKBP15 (14% identical), FKBP9 (14% identical), FKBP6 (14% identical), FKBP10 (13% identical), FKBP7 (10% identical), FKBP1B (9% identical), and 6 more.
Diseases named in the same sentence as TTC9B in open-access papers:
TTC9B is named in the same sentence as 1 disease in open-access papers, as found by Europe PMC text mining. Sharing a sentence is not in itself a finding about the gene and the disease. The quoted sentences say what the papers report.
postpartum depression (2 papers, 2014 to 2023). A type of clinical depression that occurs after childbirth. "In terms of pathogenesis, previous studies have shown that stressful life events can change the epigenetic modification of genes, and women with postpartum depression have different methylation patterns of the hp1bp3 and ttc9b genes." (PMID 38188054, 2023).